IFNA16 (interferon alpha 16)
Description:
Produced by macrophages, IFN-alpha have antiviral activities. Interferon stimulates the production of two enzymes: a protein kinase and an oligoadenylate synthetase.
Synonyms: IFN-alpha-16; IFN-alphaO
Tractability: Antibody: a drug acting on it is in phase 2 or 3 trials; its Gene Ontology location is reachable by antibodies, with high confidence; UniProt places it where antibodies can reach, with medium confidence; UniProt predicts a signal peptide or a membrane-spanning region. PROTAC: ubiquitination databases record sites on it.
Gene: Protein-coding gene on chromosome 9 (21,216,373 to 21,217,311, reverse strand). Ensembl gene ENSG00000147885.
Subcellular location: Secreted
Pathways (Reactome):
Immune System: Interferon alpha/beta signaling; Regulation of IFNA/IFNB signaling; TRAF6 mediated IRF7 activation
Disease: Evasion by RSV of host interferon responses; SARS-CoV-2 activates/modulates innate and adaptive immune responses
Hemostasis: Factors involved in megakaryocyte development and platelet production
Gene Ontology:
Molecular function: protein binding; cytokine activity; type I interferon receptor binding; cytokine receptor binding
Biological process: adaptive immune response; B cell activation involved in immune response; cellular response to virus; humoral immune response; natural killer cell activation involved in immune response; response to exogenous dsRNA; T cell activation involved in immune response; type I interferon-mediated signaling pathway; defense response
Cellular component: extracellular region
Genetic constraint (gnomAD): Loss-of-function variants: 1 observed, 0.15 expected, observed/expected ratio (o/e) 6.52. That is too few expected variants to judge how well the gene tolerates losing a copy. Missense variants: 332 observed, 219.23 expected, observed/expected ratio (o/e) 1.51, 90% interval 1.38 to 1.66. Synonymous variants: 122 observed, 82.74 expected, observed/expected ratio (o/e) 1.47, 90% interval 1.27 to 1.71.
Homologues: Orthologues: macaque IFNA16 (91% identical), pig IFN-ALPHA-15 (68% identical), pig IFN-ALPHA-9 (68% identical), pig IFN-ALPHA-13 (67% identical), pig IFN-ALPHA-8 (67% identical), pig IFNA1 (66% identical), pig IFN-ALPHA-4 (65% identical), pig IFN-ALPHA-17 (64% identical), pig IFN-ALPHA-1 (63% identical), pig IFN-ALPHA-10 (63% identical), guinea pig IFNA1 (62% identical), mouse Ifna1 (61% identical), and 31 more. Paralogues in human: IFNA4 (89% identical), IFNA10 (87% identical), IFNA17 (87% identical), IFNA21 (86% identical), IFNA7 (86% identical), IFNA14 (84% identical), IFNA5 (83% identical), IFNA8 (82% identical), IFNA2 (81% identical), IFNA6 (80% identical), IFNA13 (77% identical), IFNA1 (77% identical), and 4 more.
Diseases named in the same sentence as IFNA16 in open-access papers:
IFNA16 is named in the same sentence as 5 diseases in open-access papers, as found by Europe PMC text mining. Sharing a sentence is not in itself a finding about the gene and the disease. The quoted sentences say what the papers report.
AIDS (1 paper, 2024). A syndrome resulting from the acquired deficiency of cellular immunity caused by the human immunodeficiency virus (HIV). "Additionally, patients with Acquired Immunodeficiency Syndrome (AIDS; stage C) showed significantly higher expression of IFNA1/13, IFNA8, IFNA14, IFNA16, IFNA17, and IFNA21 mRNA." (PMID 38543729, 2024).
cardiomyopathies (1 paper, 2025). "Moreover, JAK1 and IFNA16/IFNA14 can be used for constructing models to accurately identify the two cardiomyopathies." (PMID 39704101, 2025).
IFNA16 also shares sentences with these, for which no sentence is quoted: infection (2 papers); lupus nephritis (1); viral infections (1).